ALB (albumin)
Diseases named in the same sentence as ALB in open-access papers (continued):
Sharing a sentence is not in itself a finding about the gene and the disease.
liver cirrhosis (continued). "The model included features in CPTAC: gender, age, tumor differentiation, history of liver cirrhosis, number of tumors, tumor size, tumor thrombus, tumor encapsulation, HBcAb, AFP, PTT, TB, ALB, ALT, and GGT." (PMID 32746792, 2020). "One case (0.9%) of HRV was missed, and the case had liver cirrhosis secondary to HBV, and the platelet count and albumin were 142000/μL and 40.5 g/L, respectively." (PMID 32766309, 2020). "Since the albumin in the AGR was affected by liver function, we made the survival analysis in the patients with liver cirrhosis." (PMID 31612101, 2019). "Other significant baseline risk factors for HCC development included old age, presence of liver cirrhosis, high in alcohol consumption amount, high AFP level, low albumin level, prolonged prothrombin time, and low platelet counts." (PMID 30824851, 2019). "Patients with liver cirrhosis with thrombocytopenia have lower TPO levels compared to those without thrombocytopenia, and serum TPO levels are reported to correlate with albumin levels and Child–Pugh score." (PMID 30768601, 2019). "Conversely, the levels of ALT, ALB, CHE, triglycerides, and cholesterol were higher in the CHC-only group compared to the liver cirrhosis group." (PMID 28831144, 2017). "Several demographic and clinical characteristics, such as age, liver cirrhosis, Child-Pugh stage, hemoglobin, platelet, INR, albumin, total bilirubin, creatinine, modified UICC stage, morphology of lesions, were significantly different among four groups." (PMID 27468402, 2016). "If there were growth of elderly, increase of gamma GT, decrease of albumin, increase of total bilirubin and increase of INR, it indicates that the liver cirrhosis is being enhanced." (PMID 26648983, 2015). "However, serum albumin (17.9 ± 4.4 vs 24.1 ± 6.0 g/L, p = 0.001) and transferrin (1.3 ± 0.6 vs 2.0 ± 0.5 g/L, p < 0.0001) levels were demonstrated to be significantly lower in patients with Child-Pugh C liver cirrhosis compared to those with Child-Pugh B disease." (PMID 20576106, 2010). "Yet experimental studies and meta-analyses convincingly demonstrated that treatments with BCAA augment the biosynthesis of albumin by hepatocytes, justifying the use of BCAA supplementations for elevating serum albumin levels, in particular in patients with liver cirrhosis." (PMID 41373420, 2025). "This is in line with a previous study showing positive correlations of LBP with aspartate aminotransferase and gamma-glutamyltransferase and a negative correlation with albumin in patients with liver cirrhosis." (PMID 39997462, 2025). "Previously, albumin–bilirubin (ALBI) grade, platelet–albumin–bilirubin (PALBI) grade were used to determine the prognosis of acute-chronic liver failure and acute upper gastrointestinal bleeding in liver cirrhosis." (PMID 38228667, 2024). "In treating liver cirrhosis, prioritize patients with advanced age, a history of hepatic artery embolization, recent invasive operations, history of liver cancer, recent antibiotic exposure, high APACHE II scores and low albumin." (PMID 39039452, 2024). "None of the SM species were associated with ALT, AST, albumin, CRP, leukocytes, platelet count, or creatinine in male patients with liver cirrhosis." (PMID 37176109, 2023). "In addition, a statistically significant positive correlation between FEV1 and serum albumin, and between FVC and serum albumin has been described in patients with liver cirrhosis." (PMID 37533800, 2023). "In our data, lower BMI or having liver cirrhosis did not change the result, whereas having a cancer attenuated the performance of the albumin level for predicting mortality." (PMID 35672868, 2022). "However, significant difference was noted between patients with HCC and patients with liver cirrhosis regarding serum insulin, presence of insulin resistance and liver function ALT, AST, GGT, AFP, serum albumin, GLR, TAG/HDL-C, and LAIR-1 expression." (PMID 36293412, 2022).
liver cirrhosis (continued). "There is growth hormone resistance in patients with liver cirrhosis, which leads to obstacles in the synthesis of IGF-I and its binding protein in the liver, resulting in decreased liver albumin synthesis and decreased glucose gluconeogenesis and glycogen synthesis." (PMID 35251204, 2022). "On the other hand, the mean value of albumin and platelet count decreased with the progression of liver fibrosis being lower in patients who developed liver cirrhosis (F4) than those with no liver fibrosis (F0) and liver fibrosis (F1‐F3)." (PMID 35080677, 2022). "Other characteristics significantly associated with death and rebleeding in univariate analysis included age, liver cirrhosis, gastrointestinal tumors, hematemesis, systolic blood pressure (SBP), hemoglobin (HGB), albumin (ALB), peptic ulcer bleeding, and thrombotic events in hospital." (PMID 35911402, 2022). "Albumin and prealbumin levels are closely related to the severity of liver cirrhosis, and it is not surprising that they can predict adverse outcomes in patients with HCC." (PMID 34976789, 2021). "This meta‐analysis showed that the use of terlipressin with albumin in patients with liver cirrhosis and HRS is superior to placebo and albumin alone, regarding likelihood of HRS reversal, decrease in baseline serum Cr, with a trend toward less requirement of RRT at 30 days." (PMID 34386597, 2021). "From a nutritionist point of view, there is no indication for the substitution of albumin in patients with liver cirrhosis." (PMID 31717529, 2019). "No obvious correlations with gender, HBsAg, liver cirrhosis, serum albumin, total bilirubin (TBil), glutamic-pyruvic transaminase (ALT), or glutamic-oxaloacetic transaminase (AST) were observed (P > 0.05)." (PMID 31632844, 2019). "A major advantage of this parameter compared to albumin is the fact that it is not influenced by exogenous albumin administration, a frequent treatment in patients with decompensated liver cirrhosis." (PMID 31717529, 2019). "Furthermore, recurrence‐free survival rates tended to be more favorable in patients with albumin <4.0 g/dL, microscopic vascular invasion, tumor size >2.0 cm, AFP >20 ng/dL, ALT >30 IU/L, T‐Bil >1.0 mg/dL, and liver cirrhosis." (PMID 30003195, 2018). "Non-survivors had more liver cirrhosis (18% vs. 7%, p = .003) and lower serum albumin levels (2.8 ± 0.6 vs. 3.0 ± 0.7, p < .01) than survivors." (PMID 30015549, 2018). "In liver cirrhosis, current evidence-based guidance advocates the use of HAS in large-volume paracentesis, HRS31 and SBP.32 33 The mechanism behind current usage of albumin is that of volume expansion." (PMID 30344180, 2018). "Higher serum AFB1 albumin adducts (AAAs) were observed in the individuals with liver cirrhosis than these without liver cirrhosis (1.48 ± 0.32 vs. 2.40 ± 0.91 ln fmol/mg)." (PMID 29937988, 2018). "In liver cirrhosis, tolvaptan has been reported to improve hepatic edema independent of the serum level of albumin." (PMID 29063302, 2018). "We did not observe that liver cirrhosis, albumin ≤ 35 g/L or other clinical factors correlated significantly with HBV reactivation after hepatectomy." (PMID 28122361, 2017). "This association is independent of patients’ comorbidity, severity of liver cirrhosis, and serum albumin levels." (PMID 26825885, 2016). "Among all the characteristics, age, liver cirrhosis, Child Pugh stage, hemoglobin, platelet, international normalized ratio (INR), albumin, total bilirubin, creatinine, modified UICC stage and morphology of lesions were significantly different among four groups (all P < 0.05)." (PMID 27468402, 2016). "Within the context of liver cirrhosis, several studies have highlighted the strong correlation between basal and stimulated IGF-1 serum levels and the degree of liver failure, as expressed by the Child Pugh or MELD-score, serum albumin or INR." (PMID 26186540, 2015).
liver cirrhosis (continued). "The serum ratio of branched-chain amino acids (BCAAs) to aromatic amino acids (AAAs) stabilizes at a low level in liver cirrhosis and low serum BCAA/AAA ratio reduces biosynthesis and secretion of albumin in hepatocytes, which commonly leads to the occurrence of hypoproteinemia." (PMID 26155840, 2015). "As a result of analyzing how individual characteristic index and biochemical index of blood are related to liver cirrhosis, the followings were shown: growth of elderly, increase of GGT, decrease of albumin, increase of total bilirubin, and decrease of Gamma GT." (PMID 26648983, 2015). "In conclusion, it was confirmed that there is an increase in liver cirrhosis in the following general characteristics and biochemical factors: increase of age, increase of GGT, decrease of albumin, increase of the total bilirubin, and growth of INR (International Normalized Ratio)." (PMID 26648983, 2015). "It should be mentioned that in some cases such as thyroid dysfunction, nephrotic syndrome or liver cirrhosis which the amounts of albumin is affected, and so, glycated albumin level is not a suitable indicator." (PMID 24708663, 2014). "There was no statistical difference of age, gender, hepatitis virus infection, Child-Pugh classification, liver cirrhosis and preoperative hemoglobin, platelet, alanine aminotransferase (ALT), aspartate aminotransferase (AST), albumin, or prothrombin time between the two groups (P > 0.05, resp)." (PMID 24723944, 2014). "Moreover, MSC transplantation can markedly improve the levels of ALB, Total bilirubin, and prothrombintime and the MELD scores of liver cirrhosis patients beginning at 2–3 weeks after transplantation." (PMID 22984549, 2012). "Additionally, another six genes (ALB, APOH, FABP1, FGB, FGG, and TF) were identified from our previous HCC EV-specific gene panel given their performance in distinguishing early-stage HCC from liver cirrhosis." (PMID 40307890, 2025). "Regardless of the exact percentage, conditions affecting albumin concentration, such as liver cirrhosis, may affect serum zinc levels." (PMID 38367035, 2024). "Although baseline nutritional status, liver cirrhosis, and chronic cancer may have extensive effects on the baseline serum albumin level at the initiation of CRRT, the baseline serum albumin level may also reflect the duration of inflammation before the initiation of CRRT." (PMID 35672868, 2022). "Also, albumin infusion improves renal function in non-septic patients with liver cirrhosis with AKI by improving renal blood flow autoregulation and reducing oxidative stress-related AKI." (PMID 35624664, 2022). "However, albumin also reflects liver function and its levels are decreased in advanced liver cirrhosis, with or without malnutrition." (PMID 36555953, 2022). "Although patients' age, gender, smoking, liver cirrhosis, and serum albumin were not significantly different for the development of TB infection in univariable analysis, these factors were important risk factors of TB infection and were included in multivariable analysis." (PMID 34485344, 2021). "miR-29b-3p and miR-29c-3p proved to be best related to the Model for End-stage Liver Disease (MELD)-Albumin and Albumin-Bilirubin (ALBI) scores, being in higher concentrations in patients with MELD-Albumin scores over 11 and ALBI scores over -2.6, indicating fibrosis or cirrhosis of the liver." (PMID 34104236, 2021). "Although the glycated albumin level is not influenced by hemoglobin disorders, there can be changes in its blood concentration due to disorders in albumin metabolism like nephrotic syndrome, hyper- or hypothyroidism or liver cirrhosis." (PMID 33806493, 2021). "Similarly, low albumin levels and platelet counts in the CRC group may be explained by the higher prevalence of liver cirrhosis in Phase II analysis." (PMID 30824851, 2019).
liver cirrhosis (continued). "Second, comorbidities that may have affected systemic inflammation and the serum albumin concentration (such as infection, ischemia, acute coronary disease, liver cirrhosis, and nephrotic syndrome) were not taken into consideration." (PMID 27812440, 2016). "In this study, factors that affect liver-related death were serum albumin level and the initial presence of liver cirrhosis, but not HCV viral load, indicating that liver-related mortality in HCV-infected patients seems to be mainly related to hepatic reserve function." (PMID 27656205, 2016). "Comparing the demographic characteristics between patients with and those without the pre-S deletion HBV mutants, those with the pre-S deletion mutants had a higher rate of liver cirrhosis on the non-tumor part, lower serum albumin levels, higher GGT levels, and a trend of higher ALT level." (PMID 23805222, 2013). "However, the relationship between preoperative serum albumin level and severity of liver cirrhosis has not been established in this specific group." (PMID 23285146, 2012). "Liver cirrhosis gradually develops into end-stage or non-end-stage liver failure, with liver synthesis dysfunction as the main pathological change, characterized by lack of various coagulation factors, serum albumin and α β globulin, an increase of bilirubin and so on." (PMID 37465101, 2023). "Neither the serum albumin level and platelet count, nor abdominal CT revealed any definitive evidence of liver cirrhosis, but it is considered that the patient may have had hepatopathy, because she gave a history of heavy drinking of more than 100 g of alcohol every day for more than 30 years." (PMID 20731531, 2010). "In patients with liver cirrhosis who had not developed HCC and who had taken NADs for at least 6 months, serum albumin levels were measured in 54 lactitol and 70 lactulose patients from 6 months before taking NADs to 6 months after taking NADs." (PMID 40438352, 2025). "Additional adjustment for ALT, AST, ALB, GGT, TBIL, Cr, Urea, eGFR, FBG, TG, TC, LDL - C, and HDL - C neither attenuated the magnitude of the ORs for liver cirrhosis nor affected the statistical significance (all p < 0.05)." (PMID 41458540, 2025). "In patients without liver cirrhosis, PC species were mostly not correlated with AST, ALT, the international normalized ratio (INR), bilirubin, albumin, the MELD score or creatinine." (PMID 39125730, 2024). "In patients without liver cirrhosis, all except LPC 18:2, 18:3, 20:4, 20:5 and 22:6 positively correlated with albumin." (PMID 38256273, 2024). "Serum SM species levels did not correlate with the MELD score, ALT, AST, bilirubin, albumin, INR, CRP, leukocytes, platelet count, or creatinine in female patients without liver cirrhosis (p > 0.05)." (PMID 37176109, 2023). "Serum SM species levels did not correlate with the MELD score, ALT, AST, bilirubin, albumin, INR, CRP, leukocytes, platelets, or creatinine in male patients without liver cirrhosis (p > 0.05)." (PMID 37176109, 2023). "Patients with liver cirrhosis who had regression of glucose metabolism disorders had higher levels of HOMA-β and ALB and a lower level of FIB-4 than those without regression." (PMID 35273920, 2022). "In the present study, there were significant differences in ALB, BNP, serum Na+, and Child-Pugh scores between liver cirrhosis patients with atrial arrhythmia and those without atrial arrhythmia." (PMID 34291096, 2021). "Our meta-analysis included four RCTs and 423 patients with liver cirrhosis, and the results confirmed that compared to placebo for patients with liver cirrhosis, emricasan treatment showed no improvement in MELD, INR, total bilirubin or serum albumin." (PMID 38223578, 2023). "First, although the severity of liver cirrhosis is commonly based by Child-Pugh scores or MELD scores, the database used in the present study did not allow us to identify the laboratory for bilirubin, albumin, creatinine, or prothrombin time by ICD-9 coding numbers." (PMID 23390924, 2013).
heart failure (419 papers, 2008 to 2026). Inability of the heart to pump blood at an adequate rate to meet tissue metabolic requirements. "It is well‐known that levels of bilirubin and albumin are linked with central venous pressure in patients with heart failure." (PMID 39992725, 2025). "Other biomarkers, including estimated glomerular filtration rate, urine albumin-to-creatinine ratio, and β2-microglobulin, were also proved to be associated with heart failure in patients with CKD." (PMID 40053710, 2025). "Patients with heart failure often experience edema and protein loss, leading to increased albumin loss." (PMID 40104144, 2025). "Studies have shown that low albumin levels can accelerate the progression of heart failure by causing oxidative stress and endothelial dysfunction." (PMID 40104144, 2025). "In contrast, in men, an elevated albumin/creatine ratio is more strongly associated with hospitalization for heart failure and myocardial infarction." (PMID 40731856, 2025). "An elevated CRP/ALB ratio has also been associated with frequent and repeated hospital admissions, as well as an increased risk of developing severe heart failure." (PMID 40573094, 2025). "In line with previous studies, the research indicates that low levels of albumin predict the likelihood of death from any cause in patients hospitalized for heart failure, identifying an optimal threshold at 2.9 g/dL." (PMID 40279952, 2025). "Infusing albumin was found to be markedly linked with higher in-hospital mortality among heart failure patients whose serum albumin levels were ≤ 2.9 g/dL (p < 0.001)." (PMID 40279952, 2025). "In contrast, increased albumin levels during hospitalization have been associated with a decreased risk of all-cause mortality and hospitalization within 1 year in patients with heart failure." (PMID 41030320, 2025). "Research has explored the relationship between hypoproteinemia and the prognosis of heart failure patients, revealing that low ALB levels are significantly associated with decreased survival rates." (PMID 40552149, 2025). "In our study, we found that not only the risk of myocardial infarction but also the risks of heart failure, arrhythmias, and takotsubo cardiomyopathy were increased in patients with reduced albumin levels." (PMID 38323429, 2024). "More importantly, the integration of serum albumin and creatinine into sACR has been shown to have a significant impact on the risk of all-cause mortality in heart failure, partially through its direct impact." (PMID 39027002, 2024). "Heart failure patients often experience a loss ofappetite, dyspepsia and other conditions, resulting in insufficient nutrientintake and reduced albumin synthesis." (PMID 39742221, 2024). "Previous studies have shown that low albumin levels are linked to higher risks of bleeding and heart failure in AMI patients, supporting our findings." (PMID 39902029, 2024). "There is increasing evidence that serum albumin levels are closely associated with cardiovascular diseases, such as myocardial fibrosis, adverse pulsing aortic hemodynamics, heart failure, and coronary heart disease." (PMID 37745114, 2023). "Specifically, numerous studies have demonstrated a strong association between serum albumin levels and the prognosis of cardiovascular diseases, such as atherosclerosis, myocardial infarction, and heart failure." (PMID 37745114, 2023). "Albumin indirectly affected all-cause mortality through hemoglobin (β = 0.217) and heart failure (β = −0.061)." (PMID 38831863, 2023). "In a heart failure study, low transthyretin was reported to be associated with older age and lower albumin and HB." (PMID 36960201, 2023). "By using the Cox regression model, frailty (p = 0.004), heart failure (p = 0.007), EF% (p = 0.043), albumin (p = 0.018) were associated with all-cause mortality." (PMID 37233180, 2023).